MIR520E (microRNA 520e)
Synonyms: hsa-mir-520e; MIRN520E
Gene: MicroRNA gene on chromosome 19 (53,675,711 to 53,675,797, forward strand). Ensembl gene ENSG00000207599.
Gene Ontology:
Biological process: miRNA-mediated post-transcriptional gene silencing
Homologues: Orthologues: chimpanzee ptr-mir-520e (100% identical). Paralogues in human: MIR516A1 (87% identical), MIR520C (87% identical), MIR516A2 (86% identical), MIR516B1 (85% identical), MIR518D (85% identical), MIR518F (85% identical), MIR519A2 (85% identical), MIR519C (85% identical), MIR523 (85% identical), MIR518C (84% identical), MIR520F (84% identical), MIR517A (83% identical), and 12 more.
Diseases named in the same sentence as MIR520E in open-access papers:
MIR520E is named in the same sentence as 1 disease in open-access papers, as found by Europe PMC text mining. Sharing a sentence is not in itself a finding about the gene and the disease. The quoted sentences say what the papers report.
tumours (1 paper, 2024). "We identified MIR182, MIR183, MIR371, MIR373, MIR512-1, MIR512-2, MIR515-1, and MIR520e exhibiting high expression and MIR216b, MIR887, MIR9-2, and MIR9-3 exhibiting low expression in NANOG H/L tumours." (PMID 38693576, 2024).